BRAF (B-Raf proto-oncogene, serine/threonine kinase)
Diseases named in the same sentence as BRAF in open-access papers (continued):
Sharing a sentence is not in itself a finding about the gene and the disease.
breast carcinoma (264 papers, 2009 to 2026). "The association of BRAF expression and CNAs with breast cancer clinicopathologic characteristics was analyzed." (PMID 38919805, 2024). "Our analysis of the METABRIC dataset revealed that BRAF expression and CNAs were associated with adverse clinicopathologic tumor features and poor prognosticators in patients with breast cancer." (PMID 38919805, 2024). "While the activation of the PI3K/Akt pathway is frequently linked to HER2-positive breast cancer, less effect is observed for BRAF expression on the tumor biology of this molecular subtype." (PMID 38919805, 2024). "The RAF/MAP kinase cascade is highly mutated in cancer, RAS mutations are found in ∼30% of all human cancers, and the most active activator of this pathway is BRAF, which is reported to be mutated in ∼7% of cancers, including breast cancer." (PMID 37128318, 2023). "While canonical mutations in Ras/MAPK genes (for example KRAS G12V and BRAF V600E) are rare in breast cancer, Ras/MAPK is often overactivated in response to pathway deregulation." (PMID 35850776, 2022). "In other cancer types such as pancreatic cancer, prostate cancer and breast cancer, BRAF mutations were only found at low relative frequencies (1.62%, 1.54% and 0.63%, respectively)." (PMID 36275468, 2022). "A BRAF mutation is rare in breast cancer and TNBC, but several-BRAF V600E-driven TNBC cases have been reported." (PMID 36011019, 2022). "There is a 2020 study that examined the association of the BRAF/MEK pathway with the risk of breast cancer recurrence." (PMID 34934548, 2021). "While therapy using HER2-inhibition is genuinely successful in primary or advanced HER2-positive breast cancer, BRAF inhibition is often undertaken by downstream mutations leading to time-dependent relapses." (PMID 34262462, 2021). "BRAF mutations are very uncommon in breast cancer representing around 0%–1.2% in public databases of both localized curable primary and MBC and 1%–4% of clinically advanced MBC in the current study." (PMID 33314633, 2021). "In in vivo and xenograft models of a brain-tropic Her2-positive, BRAF-mutated breast cancer cell line, pazopanib prevented the growth of brain metastasis in association with reduced MAPK pathway activation but no change in markers of angiogenesis." (PMID 31123606, 2019). "BRAF mutations were also described in breast cancer, with the V600E being the most reported." (PMID 38919805, 2024). "Therefore, this study is aimed at comprehensively analyzing BRAF expression and gene copy number status in breast cancer and its association with clinicopathologic characteristics and survival." (PMID 38919805, 2024). "Moreover, it has been shown that the expression of BRAF/MEK pathway activity was linked to estrogen-dependent breast cancer." (PMID 36014478, 2022). "In cancer types with low frequencies of BRAF mutations such as leukemia, breast cancer, myeloproliferative neoplasms, head and neck cancer and esophagogastric cancer the author found high proportions of BRAF variants of unknown significance." (PMID 36275468, 2022). "Of these, one patient with breast cancer and a BRAF G469E mutation (class 2) had a partial response (response rate 3%), one patient with lung adenocarcinoma and a BRAF G469A mutation remains on therapy at 20.4 months, and an additional 3 patients had progression-free survival (PFS) of > 6 months." (PMID 33216832, 2020). "Furthermore, although mutations in the RAS or BRAF genes are rarely observed in the overall majority of breast cancers, they occur more frequently in cell lines derived from basal type breast cancers, a rare, but difficult to treat subtype." (PMID 21752278, 2011). "BRAF inhibitors could be a promising therapeutic option for a selected group of patients with breast cancer, calling for further exploration of the mutational profile of BRAF in breast cancer." (PMID 38919805, 2024).
breast carcinoma (continued). "However, in certain breast cancer subtypes with BRAF mutations, targeting them may offer viable treatment options." (PMID 37885828, 2023). "Deactivating variants are less similar; for example, p.His371Tyr two positions N-terminal in CHEK2 in breast cancer and the equivalent N-terminal position p.Leu597Val in BRAF was shown to be activating." (PMID 41152984, 2025). "Tumoral BRAF mRNA expression and CNAs along with demographic and tumor data for patients with breast cancer were retrieved." (PMID 38919805, 2024). "Nevertheless, the impact of BRAF expression on the development and progression of breast cancer is inconclusive." (PMID 38919805, 2024). "Although growing evidence has investigated the expression of BRAF and its role in several human cancers, the impact of BRAF expression in breast cancer is less clear." (PMID 38919805, 2024). "Analysis of the METABRIC dataset revealed a significant role of the BRAF gene and its CNAs in relation to unfavorable clinicopathologic characteristics and poor prognosis in breast cancer." (PMID 38919805, 2024). "BRAF mRNA expression correlated positively with NPI in this analysis supporting its adverse impact on the prognosis of patients with breast cancer." (PMID 38919805, 2024). "The growth hormone receptor (GHR) is overexpressed in many solid tumors and promotes tumor proliferation, progression, and metastasis in breast cancer via the BRAF/MEK/ERK pathway." (PMID 37245006, 2023). "Vemurafenib and dabrafenib, two BRAF inhibitors, have demonstrated potential as targeted treatments for BRAF-mutant breast cancer." (PMID 37711177, 2023). "A further study of BRAF/MEK pathway activity from TCGA and 43 microarray datasets found downregulation of BRAF/MEK pathways in breast cancer compared with normal breast tissue, except for HER2-positive and triple-negative tumors." (PMID 36358725, 2022). "The identification of novel connections between tumor biology and drug response highlighted an association between BRAF inhibitors efficacy and BRAF/MITF overexpression in breast cancer." (PMID 36304921, 2022). "Human breast cancers rarely show KRAS and BRAF mutations, whereas mutations in genes that activate the PI3K-Akt pathway have been reported." (PMID 33793658, 2021). "MDA-MB-231 display mutations in both KRAS and BRAF, the work summarized below utilizes a combination of MDA-MB-231 and transformed MCF-10A cells to dissect the contributions of autophagy to breast cancer pathogenesis." (PMID 34503118, 2021). "As another example, BRAF was upregulated in the subset of breast cancers with 7q34 amplification (FDR = 0.0081)." (PMID 33941236, 2021). "GHR was recently reported to mediate cell progression and apoptosis via the BRAF/MEK/ERK signaling pathway in breast cancer." (PMID 33330065, 2020). "(c) UAG (100 pM) suppresses cell growth of basal-like and mesenchymal-like TNBC breast cancer cell lines that are WT for BRAF and KRAS (6–9 replicates/group)." (PMID 32667883, 2020). "On the basis of the results presented earlier, we conclude that GHR mediates breast cancer cell progression and apoptosis through controlling cell cycle in G1–S phase transition as a regulator of the BRAF/MEK/ERK signaling pathway." (PMID 32069380, 2020). "The authors added that the adoption of this technology in hospitals has already improved the manner in which healthcare practitioners detect and monitor KRAS, BRAF, and EGFR mutations in patients with lung, colon, and breast cancer, respectively." (PMID 29728089, 2018). "BAIAP2 was associated with overall and ER+ breast cancer; CALM2 with overall breast cancer; CSNK2A1 with ER+ breast cancer; and BRAF, BAD, and MAPK3 with ER− breast cancer." (PMID 27942580, 2016).
breast carcinoma (continued). "The most significant gene associations (P⩽0.01) were BAIAP2 and CALM2 for overall breast cancer; BAIAP2 and CSNK2A1 for ER+ breast cancer; and BRAF, BAD, and MAPK3 for ER− breast cancer." (PMID 27942580, 2016). "Taken together, these data show that BRAF is a novel alcohol and estrogen responsive gene, which is overexpressed in breast cancer patients with poorer DSS parameters." (PMID 26661278, 2015). "Cu is required for binding to the dual specificity mitogen-activated protein kinase kinase 1 MEK1 and promotion of mitogen-activated protein kinase MAPK signaling and tumorigenesis by v-raf murine sarcoma viral oncogene homolog B BRAF in mammary tumors." (PMID 26583055, 2015). "There is also evidence that breast cancer cell lines with a basal phenotype have a higher frequency of mutations in BRAF, KRAS, and HRAS than luminal breast cancer cell lines." (PMID 20604919, 2010). "Our study indicated a higher expression of BRAF in the younger premenopausal patients which could explain, at least in part, the genetic background for breast cancer in this patient population along with their advanced clinicopathologic features at diagnosis." (PMID 38919805, 2024). "Patients with breast cancer may have different characteristics that make BRAF expression less predictive of pathological stage and lymph node metastasis." (PMID 38919805, 2024). "Therefore, BRAF gain and high-level amplification CNAs can be employed as markers of unfavorable characteristics of breast cancer." (PMID 38919805, 2024). "BRAF (a component of the MAPK pathway) mutations are rare in breast cancer and TNBC, and no clinical trials have directly targeted BRAF for TNBC treatment." (PMID 37627272, 2023). "The proportion of alterations of KRAS and BRAF differed significantly among breast cancer subtypes (Fisher exact test two-sided p = 1.566 × 10−12 and p = 1.355 × 10−11, respectively), with both genes more frequently altered, mainly due to amplification, in basal-like tumors." (PMID 36358725, 2022). "If these studies find the drug to be tolerable, it would be highly interesting to extend the approach to clinical studies that combine SHP2 inhibitors with PI3K, MEK, BRAF or ALK inhibitors in breast cancer and further types of tumors which exhibit aberrations in the associated pathways." (PMID 35365185, 2022). "Copy number (CN) alterations in ctDNA were also associated with breast cancer subtype, with CN alterations in MYC, PIK3CA, EGFR, CCNE1, CDK6, BRAF and MET more common in TNBC (q = 0.01, q < 0.0001, q = 0.001, q < 0.0001, q = 0.0003, q = 0.0002 and q = 0.01, respectively)." (PMID 33893289, 2021). "Silencing GHR inhibited the activation of the BRAF/MEK/ERK signaling pathway, which might be one of the mechanisms underlying breast cancer progression inhibition caused by GH suppression." (PMID 32069380, 2020). "Based on the data obtained using a panel of breast cancer cell lines and effects seen in patient-derived tumor cells, we also identify the subset of breast cancers that will be resistant to treatment, that is TNBCs with KRAS or BRAF mutations, or TNBCs with high MAPK activity." (PMID 32667883, 2020). "To verify whether GHR is associated with breast cancer progression by modulating the BRAF/MEK/ERK signaling pathway, we evaluated the roles of GHR silencing in the expression of p‐BRAF, p‐MEK and p‐ERK." (PMID 32069380, 2020). "However, BRAF and KRAS mutations are rare in breast cancer with BRAF and KRAS mutated in 0.45% and 0.54% of The Cancer Genome Atlas (TCGA) breast cancer genomes respectively." (PMID 30658422, 2019). "Furthermore, a large percentage of breast cancers were found to have measurable levels of mutations in critical genes of the MAP kinase pathway (i.e., KRAS, HRAS, and BRAF)." (PMID 30813596, 2019). "Since the KIAA1549-BRAF fusion is also found in adult cancers such as breast cancer and sarcomas, our findings could inform emergent drug resistance in multiple cancers harboring BRAF-fusions." (PMID 29156677, 2017).
breast carcinoma (continued). "It was reported that breast cancer rarely possessed ERK pathway kinases mutations, BRAF (2%), KRAS (5%), and HRAS (1%) mutations occur at even lower frequency in TNBC, only a few of studies recognized breast cancer as a good candidate of ERK pathway targeting therapy." (PMID 29296238, 2017). "A SNP in BRAF (rs114729114) showed an OR of 2.04 (P=4.9×10−6) for ER− breast cancer." (PMID 27942580, 2016). "Knock-down of BRAF, moreover, prevented the proliferation of breast cancer cells." (PMID 26661278, 2015). "Kaplan-Meier survival analysis of patients based on BRAF expression levels showed statistically significant DMFS and DSS outcomes in ER+ breast cancer patients (p = .02 and 0.03, respectively), where women with higher expression of the BRAF mRNA responded more poorly to endocrine therapy." (PMID 26661278, 2015). "Moreover, constitutively present pS-EphA2 in MDA-MB-231 human breast cancer cells harbouring KRAS and BRAF mutations and Panc-1 human pancreatic cancer cells carrying KRAS mutation was also resistant to PI3K inhibition." (PMID 26158630, 2015). "The absence of BRAF mutation is also somewhat expected and is supported by the stronger association between basal cell breast cancer lines and BRAF mutation (since the majority of MBCs are of a luminal subtype)." (PMID 23971979, 2013). "Among disease entities with more than 10 patients tested, no BRAF mutations were found in squamous cell cancers of head and neck, uterine cancers, breast cancers, NSCLC, sarcomas, and adenocarcinomas of stomach and esophagus." (PMID 21829508, 2011). "Potentially actionable molecular alterations include agnostic targets (NTRK1-2-3, RET fusions, BRAF V600E mutations, microsatellite instability, high tumor mutational burden), or tissue-specific targets, such as EGFR mutation in NSCLC or PIK3CA mutations in breast cancer." (PMID 39766151, 2024). "We screened the antitumoral activity of ipatasertib and taselisib in five breast cancer cell lines, MDAMB231, MDAMB468, MCF7, SKBR3 and MDAMB361, each one having different expression of ER and HER2 receptors, or mutations involving PI3K/AKT and BRAF/RAS pathways." (PMID 35761360, 2022). "Reports indicate that TMB in BRAF‐altered MBC is generally higher, and hence may be a potential biomarker of ICPI efficacy, but larger studies are lacking with regard to the predictive status of BRAF mutations in breast cancer." (PMID 33314633, 2021). "When BRAF V600E and non-synonymous changes in KRAS or NRAS were considered, methylation of the 5′UTR of C7orf49 and of the probe cg00172872 in the intergenic region on 12q21.33 remained significantly associated with trametinib in pancancer and breast cancer (5.24 × 10–13 ≤ pFDR ≤ 0.0023)." (PMID 33676569, 2021). "Interestingly, we identified outlier phosphosites in genes not previously implicated in breast cancer through genomic profiles, such as BRAF p.S447, p.S750 and HSP90AB1 p.Y56 and p.S169." (PMID 28348404, 2017). "The diagnosis-specific GPA score adds EGFR, BRAF, hemoglobin, HER2, and breast cancer subtype as factors that enhance the scoring accuracy for the respective tumors." (PMID 38668035, 2024). "Among the six fusions identified in breast carcinoma samples of the 38 samples examined, three involved NOTCH2, and one each involved FGFR3, NTRK3, and BRAF." (PMID 38800398, 2024).
breast carcinoma (continued). "Concerning breast cancer, alcohol-induced genes BRAF and ITPR1 presented a higher expression in ER+ breast cancer patients with a higher alcohol intake." (PMID 39125744, 2024). "The same MCF-7 breast cancer cell line was used to reveal the UA modulating activity on the PLK1, IKK/NF-kB, and BRAF/ERK pathways; UA induced MCF-7 cells apoptosis by suppressing the phosphorylation of BRAF, ERK1, and PLK1 levels." (PMID 35887090, 2022). "In breast cancer, ETV4 was transcriptionally activated by the ECM via the integrin/BRAF/TAK1/ERK pathway." (PMID 34623791, 2021). "The expression status of the BRAF gene did not influence the overall survival of patients with breast cancer in this analysis of the METABRIC dataset." (PMID 38919805, 2024). "NF1 loss-of-function mutations, RTKs mutations such as ERBB2 activating mutations, as well as alterations in other MAPK pathway genes (EGFR, KRAS, BRAF, and MAP2K1) were found to be enriched in endocrine-resistant advanced ER+ breast cancer compared to early-stage ER+ breast cancer." (PMID 38003387, 2023). "This has been completed in HCT-116 CRC cells and MCF7 breast cancer cells treated with conventional chemotherapies and in HCT-116, HT-29, and KM12C CRC cells treated with MEK, TRK, tyrosine kinase, RET, BRAF, PARP, PI3K, and GSK-3 inhibitors as well as Imipridones." (PMID 35205776, 2022). "BRAF is involved in the processes of EMT, stemness or metastasis in breast; thus, different BRAF status in two breast cancer cell lines might affect the EMT signaling pathways after SLC27A4 silencing." (PMID 30388870, 2018). "The human breast cancer cell line MCF-7 were used as wild-type for both KRAS and BRAF genes." (PMID 23536897, 2013). "Since miR-129-5p expression in various cancer entities (e.g., endometrial cancer, breast cancer and gastric cancer) is mediated by EZH2, an epigenetic modulator of H3K27me3 and DNA methylation, we investigated if EZH2 is mediated by BRAF/MEK pathway inhibition." (PMID 34063443, 2021). "Interestingly, in breast cancer, ERK activation was less pronounced in MDA-MB-231, a cell line harbouring KRAS G38A and BRAF G464V mutations, compared with the non-transformed epithelial cell line MCF10a." (PMID 21730974, 2011).